KLF4 (KLF transcription factor 4)
Diseases named in the same sentence as KLF4 in open-access papers (continued):
Sharing a sentence is not in itself a finding about the gene and the disease.
breast tumor (23 papers, 2010 to 2025). "The transcript and protein levels of KLF4 are increased during breast tumor progression and its nuclear localization has been associated to an aggressive phenotype in early stages of breast tumors." (PMID 20126619, 2010). "Results from recent pathophysiological and “The Cancer Genome Atlas (TCGA)” studies have unveiled an oncogenic property for KLF4 in breast carcinogenesis, although its underlying mechanism in breast tumor initiation and invasion remains unclear." (PMID 33231937, 2020). "It was showed that ANGPTL4 and KLF4 showed significantly higher expression levels in breast tumor tissues compared to adjacent normal tissues." (PMID 40616161, 2025). "Kruppel-like transcription factors (KLFs), which play a key role in maintaining pluripotency, and KLF4/KLF5 have been shown to be elevated in aggressive primary breast tumors, promoting metabolic reprogramming and tumor progression." (PMID 40616161, 2025). "PRMT5 promotes the expansion of stem cells through histone methylation and the expression of forkhead box P1 (FOXP1) and Kruppel-like Factor 4 (KLF4), thereby enabling the development of breast tumors and chemotherapy resistance." (PMID 36230903, 2022). "The results showed that the methylation level of the CpG sites (−148 bp) in the KLF4 promoter was significantly higher in breast tumor tissues than in adjacent normal tissues." (PMID 34150611, 2021). "Consistent with the observation in the cultured‐cell model, KLF4 knockdown significantly decreases the breast tumor progression in comparison with the control group." (PMID 33231937, 2020). "While loss of KLF4 function induces EMT-like morphological changes, forced expression of KLF4 in the highly metastatic MDA-MB-231 breast tumor cell line was sufficient to restore E-cadherin expression and suppress migration and invasion." (PMID 26823670, 2016). "It is believed that KLF4 is expressed at low levels in normal breast epithelium, but over-expressed during breast tumor progression." (PMID 27323810, 2016). "We next examined the transcript abundance of KLF4/5 as determined by RNAseq analysis of patient breast tumors via The Cancer Genome Atlas (TCGA) Research Network." (PMID 25789974, 2015). "In TNBC cells, KLF4 directly regulates miR-206 transcription, and depletion of KLF4 consistently results in loss of the vast majority of miR-206.36, 37 In this study, we identified KLF4 and miR-206 as critical promoters of breast tumor cell survival." (PMID 26053033, 2015). "Collectively, these results link pluripotency factor signaling and the enhanced cell survival of MaCSCs, supporting roles of KLF4-miR-206 signaling for breast tumor cell survival, chemoresistance, and tumor initiation through the repression of PDCD4 and CX43." (PMID 26053033, 2015). "To this end, we measured the protein expression levels of PRMT5 and KLF4 in human breast tumor and adjacent normal tissue by immunohistochemistry (IHC)." (PMID 26420673, 2015). "Across 890 breast tumors, the transcript abundance for KLF4, KLF5 and MCL1 was positively correlated." (PMID 25789974, 2015). "The protein levels of both PRMT5 and KLF4 are significantly higher in breast tumor tissues than that of in the adjacent normal tissues, where their expression are well correlated with the histological grade." (PMID 26420673, 2015). "KLF4/5 were positively correlated with MCL1 in primary breast tumors, and enforced expression of MCL1 was sufficient to rescue the lapatinib sensitivity of KLF4/5-deficient cells." (PMID 25789974, 2015). "Together, these results indicate that Klf4 activity increases primary breast tumor growth but prevents its metastatic spread." (PMID 23451207, 2013). "KLF4 has been reported to act as an oncogenic factor in breast tumors." (PMID 39201539, 2024). "Also, the Western blot analysis showed that the KLF4 level was significantly lower in breast tumor tissues compared with normal tissues." (PMID 34150611, 2021).
breast tumor (continued). "To test whether deregulation of KLF4 protein stability by aberrant PRMT5 affects transformation of mammary gland epithelial cell or breast tumor progression, we engineered MCF10A and MCF7 cell lines with stable and inducible expression of KLF4 and KLF4-3K42." (PMID 26420673, 2015). "In any single breast tumor subtype or in all tumors combined, KLF4 on its own had little effect." (PMID 25789974, 2015). "Finally, Klf4 promotes breast tumor development and is upregulated in 70% of breast tumors." (PMID 34195082, 2021). "Lack of KLF4 and p21 expression has been associated with an accumulation of aggressive features in neuroendocrine lung tumors, and KLF4 is presented because of an aggressive phenotype in early-stage breast tumors." (PMID 27153563, 2016). "Stabilization of KLF4 in BC cells increases oncogenic pathways such as EGF/EGFR, MAPK, and CDK1, promoting cell growth in mammary gland and breast tumor cells." (PMID 39201539, 2024). "Both KLF4 and PARP1 protein levels were significantly higher in breast tumor tissues than in adjacent normal tissues." (PMID 33231937, 2020). "There are only a few established links between the KLFs, anti-apoptotic BCL2 family proteins and HER2.52, 53, 54 In this study, we observed coexpression of KLF4/5 and MCL1 in human breast tumors and breast cancer models." (PMID 25789974, 2015). "Within the Sp1/KLF family of transcription factors, only KLF4 and KLF5 have been further investigated in the context of breast tumor environment." (PMID 20126619, 2010). "Thus, the data support KLF4 as a key CSC-related transcription factor, reversely regulated by SIRT1 in breast tumors." (PMID 30038266, 2018).
esophageal cancer (22 papers, 2011 to 2023). A primary or metastatic malignant neoplasm involving the esophagus. "As a direct target of miR-7-5p, KLF4 mediates its inhibition of the proliferation and migration of esophageal cancer cells through the regulation of WNT3A and β-catenin protein." (PMID 36761967, 2023). "Intriguingly, miR-7-5p downregulates KLF4 in colorectal cancer as well as in esophageal cancer, but this biological downregulation inhibits tumorigenesis of esophagus cancer." (PMID 36311891, 2022). "Among patients with esophageal cancer, those who had a history of drinking 5 days a week had lower KLF4 expression." (PMID 34367275, 2021). "miR‐10b expression has also been shown to correlate with the migration and invasion of human esophageal cancer cell lines through regulation of Kruppel‐like factor 4 (KLF4) expression." (PMID 27592860, 2016). "One of the cellular targets for miR-10b, KLF4 (Kruppel-like factor 4) has been identified in human esophageal cancer cell lines." (PMID 27070574, 2016). "MiR-10b expression has subsequently been shown to correlate with the migration and invasion of human esophageal cancer cell lines through regulation of Kruppel-like factor 4 (KLF4) expression." (PMID 24216130, 2013). "However, KLF4 showed a facilitative effect on metastasis in advanced squamous cervical and esophageal cancers, which is regulated by miR-7-5p." (PMID 36761967, 2023). "It is confirmed that downregulation of miR-7-5p could significantly induce apoptosis of esophageal cancer cells by suppression of binding to Krüppel-like factor 4 (KLF4)." (PMID 36349193, 2022). "For example, KLF4 was reported to suppress cell migration and invasion in esophageal cancer." (PMID 30658712, 2019). "Also, through regulation of Kruppel-like factor 4 (KLF4) expression in human esophageal cancer cell lines, miR-10b was found to induce tumor migration and invasion." (PMID 29262659, 2017). "Furthermore, KLF4 could also be regulated post-transcriptionally by microRNA targeting, as found in human esophageal cancer cell lines." (PMID 22937066, 2012). "The stem cell markers were detected by qPCR in Eca109 cells, and the results showed that overexpression of RBBP7 upregualted the expressions of esophageal cancer stem cell markers, including SOX2, KLF4, NANOG, and OCT3/4." (PMID 35538026, 2022). "For example, high expression of miR-10b reduces Krüppel-like factor 4 (KLF4) tumor suppressor expression levels, which are reported to suppress esophageal cancer cell migration and invasion." (PMID 29280958, 2017). "Similarly, KLF4 decreased cell viability following ROS-induced DNA damage, increased anoikis and repressed pro-survival baculoviral IAP repeat-containing 5 (BIRC5) in esophageal cancer cells." (PMID 35406507, 2022). "Importantly, our results identifying KLF4 as a target of miR-2909 in B-ALL are similar to published reports of miRNA-145-mediated repression of KLF4 in human embryonic stem cells and miR-10b regulation of KLF4 in human esophageal cancer cell lines." (PMID 25037230, 2014).
liver cancer (21 papers, 2007 to 2025). An epithelial or non-epithelial malignant neoplasm that arises from the liver. "For example, loss of hetero-zygosity for Klf4 and Klf5 has been found in colon, stomach, breast, prostate and liver cancers." (PMID 17925037, 2007). "MEOX2 activates KLF4 transcription, further enhancing the stemness traits of CSCs, thereby promoting liver cancer growth and recurrence." (PMID 39995670, 2025). "Schlegel reported that conditioned medium extracted from mouse fibroblasts increased the expression of stemness genes, including Sox2, Oct4, Nanog, and Klf4, in liver cancer cells." (PMID 36348351, 2022). "Consistent with our previous finding showing that KLF4 suppresses liver cancer growth, the results of this study showed that DUB3 inhibited HCC cell proliferation in vitro and tumor growth in vivo in a KLF4-dependent manner." (PMID 35383144, 2022). "Liver cancer cells can be reprogrammed into induced cancer stem cells (iCSCs) by exogenous expression of the reprogramming transcription factors Oct4, Sox2, Klf4 and c-Myc (OSKM)." (PMID 27894081, 2017). "Additionally, KLF4 suppresses the growth and migration of human liver cancer cells by upregulating P-cadherin (CDH3) expression." (PMID 39995670, 2025). "Also, the expression of ANXA3 which promotes angiogenesis, drug resistance, and stemness in HCC, and the expression of KLF4 which is one of the Yamanaka factors that also regulates liver cancer stem cell plasticity, increased upon regorafenib treatment." (PMID 34458250, 2021). "In liver cancer cells, VDR is present in human HCC lines and patient samples, potentially regulated by KLF4." (PMID 41041128, 2025). "In addition, we discovered that only a higher degree of macrophage infiltration was associated with increased expression of KLF4 in liver cancer tissues as well as adjacent non-tumor tissues, indicating that KLF4 was likely more important for macrophage infiltration in HCC TIME." (PMID 36936440, 2023). "In this study, we first established C3A-derived liver cancer stem cells by OSKM method [OCT4, SOX2, KLF4, and c-MYC], termed C3A-induced cancer stem cells (C3A-iCSCs) which acquired self-renewal and stemness abilities." (PMID 26540347, 2015). "Our studies indicated that KLF4 could directly bind to the promoter of EpCAM and increase the number of EpCAM+/CD133+ liver cancer stem cells (LCSCs) in the HuH7 HCC cell line." (PMID 32408542, 2020). "Moreover, the up-regulation of some genes related to the stemness of cancer cells, such as EpCAM, CD133, CD44, Oct4, Nanog, KLF4 and Sox4, in USP16-depleted liver cancer cells also suggests a stemness-suppressing role for USP16." (PMID 27633997, 2016).
pulmonary fibrosis (20 papers, 2011 to 2026). Chronic progressive interstitial lung disorder characterized by the replacement of the lung tissue by connective tissue, leading to progressive dyspnea, respiratory failure, or right heart failure. "Mechanically, we revealed that circZNF609 regulates pulmonary fibrosis via miR-145-5p/KLF4 axis and circZNF609-encoded peptides." (PMID 38105235, 2023). "To further investigate mechanisms underlying the protective role of KLF4 in SMA+ cells during lung fibrosis, we evaluated the effects of siRNA-mediated Klf4 knockdown in murine airway SMCs." (PMID 34893592, 2021). "Thus, we hypothesized that although KLF4 has opposing cell type-specific roles in lung fibrosis, changes in the pulmonary environment caused by silica dust or bleomycin led to the transformation of PDGFR-β + cells into SMA + myofibroblasts." (PMID 38105235, 2023). "In bleomycin-induced pulmonary fibrosis, KLF4 was downregulated in the fibrotic area, and KLF4 overexpression attenuated bleomycin-induced pulmonary fibrosis, consistent with our observations." (PMID 38105235, 2023). "For example, the process of pulmonary fibrosis was promoted by inducing M2-typed polarization via the activation of the STAT-6/KLF-4/PPAR-γ signaling pathway." (PMID 37894541, 2023). "Our previous study revealed that KLF4 attenuates bleomycin (BLM)-induced pulmonary fibrosis (PF) by inhibiting TGF-β1-induced epithelial–mesenchymal transition (EMT)." (PMID 37762310, 2023). "H&E, Masson and β-gal staining indicated that the severity of lung fibrosis and collagen fiber accumulation were decreased in KLF4-overexpressing group." (PMID 35508454, 2022). "In conclusion, the present study demonstrates that the transcription factor KLF4 attenuates bleomycin-induced lung fibrosis by protecting TERT expression and telomere length." (PMID 35508454, 2022). "Collectively, these results demonstrate that KLF4 restoration via administration of APTO-253 has the potential to ameliorate pulmonary fibrosis even in a persistent model with a high degree of relevance to chronic fibrosing conditions such as IPF." (PMID 35852857, 2022). "We also administered a potentially novel small molecule inducer of KLF4 that both protected mice from peak pulmonary fibrosis and elicited resolution in a repetitive bleomycin model that is otherwise persistent." (PMID 35852857, 2022). "The results showed that AECs in bleomycin-induced pulmonary fibrosis model mice underwent senescent, and the expression of KLF4 and TERT was significantly decreased." (PMID 35508454, 2022). "In view of our in vitro findings demonstrating that both endogenous and ectopically expressed KLF4 restrains multiple parameters of fibroblast activation, we sought to assess the importance of fibroblast KLF4 as a potential brake on lung fibrosis in vivo." (PMID 35852857, 2022). "Conditional deletion of KLF4 from fibroblasts potentiated the peak degree of pulmonary fibrosis and abrogated the subsequent spontaneous resolution in a model of transient fibrosis." (PMID 35852857, 2022). "Then we tested KLF4 expression and senescence markers in pulmonary fibrosis old mouse (6 months old) models induced by bleomycin tracheal instillation." (PMID 35508454, 2022). "Taken together, in the context of lung fibrosis, our results indicate that KLF4 plays opposing roles in PDGFR-β+ cells and SMA+ cells and highlight the importance of further studies of interactions between distinct mesenchymal cell types." (PMID 34893592, 2021). "Mesenchymal cells change profoundly during the pathogenesis of lung fibrosis, and our results indicate that KLF4, a key regulator of cell transitions, is profibrotic in PDGFR-β+ cells and, through noncell autonomous effects, is antifibrotic in SMA+ cells." (PMID 34893592, 2021). "Together, these findings suggest Klf4 deletion in SMA+ cells worsens bleomycin-induced lung fibrosis at least partly by increasing secretion of CCL2." (PMID 34893592, 2021).
pulmonary fibrosis (continued). "Herein, the authors show that during lung fibrosis, these distinct effects can be attributed to mesenchymal cell-type specific functions of KLF4." (PMID 34893592, 2021). "In conclusion, AOBEE promoted KLF4 degradation leading to the attenuation of pulmonary fibrosis by inhibiting TGFβ1–smad/p38MAPK–lnc865/lnc556–miR-29b-2-5p–STAT3 signal pathway." (PMID 33929970, 2021). "Our previous work showed that KLF4 attenuated lung fibrosis via an inhibition of epithelial-mesenchymal transition (EMT), which also played an important role in cancer metastasis." (PMID 31969824, 2019). "The severity of lung fibrosis and collagen fiber accumulation were decreased in KLF4-overexpressing transgenic mice as shown by H&E, Masson staining, the Aschoff score and hydroxyproline analysis." (PMID 29158503, 2017). "Transgenic mice with overexpression of KLF4 were subjected to bleomycin-induced pulmonary fibrosis model and showed attenuated lung fibrosis and EMT compared to wild type group." (PMID 29158503, 2017). "Overexpression of KLF4 significantly decreased the percentage of cells undergoing EMT in pulmonary fibrosis model." (PMID 29158503, 2017). "Overexpressing of KLF4 inhibited bleomycin-induced pulmonary fibrosis and EMT in vivo and attenuate TGF-β1-induced EMT in AECs in vitro." (PMID 29158503, 2017). "The proportion of cells undergoing EMT in lungs of bleomycin-induced pulmonary fibrosis model with overexpression of KLF4 was about 3.8%." (PMID 29158503, 2017). "Here, we report, for the first time, that KLF4 inhibited bleomycin-induced pulmonary fibrosis in vivo." (PMID 29158503, 2017). "Our results showed that KLF4 attenuated bleomycin-induced pulmonary fibrosis and EMT in vivo and TGF-β1-induced EMT in AECs in vitro." (PMID 29158503, 2017). "Epithelial KLF4 is a promising potential target for further understanding the mechanism and developing novel strategy for the treatment of lung fibrosis in IPF and other EMT-related disease." (PMID 29158503, 2017). "Our results demonstrates that KLF4 plays an important role in bleomycin-induced lung fibrosis through suppressing TGFβ1-induced EMT." (PMID 29158503, 2017). "In bleomycin-induced pulmonary fibrosis, the expression of KLF4 was decreased, especially in the fibrotic area." (PMID 29158503, 2017). "One limitation of our study is that reason why KLF4 was down-regulated in pulmonary fibrosis still needs to be further investigated." (PMID 29158503, 2017). "In conclusion, the present study demonstrates that the transcription factor KLF4 attenuates bleomycin-induced lung fibrosis and EMT in vivo and TGF-β1-induced EMT in vitro." (PMID 29158503, 2017). "Mechanistically, KLF4 regulates key signaling pathways involved in pulmonary fibrosis." (PMID 40640934, 2025). "KLF4 could be a promising potential target for further understanding the mechanism and developing novel strategy for the treatment of lung fibrosis." (PMID 35508454, 2022). "Taken together, this study identified that KLF4 might be a promising potential target for further understanding the mechanism and developing novel strategy for the treatment of lung fibrosis in IPF." (PMID 35508454, 2022). "Transgenic mice with conditional deletion of KLF4 in fibroblasts exhibit worse peak lung fibrosis." (PMID 35852857, 2022). "The results suggest that KLF4 has a protective effect on pulmonary fibrosis." (PMID 35508454, 2022). "Further studies are needed to explore the role of KLF4 in IPF lung fibrosis." (PMID 35508454, 2022). "In lung-resident mesenchymal stem cells (LR-MSCs), KLF4 transcription level was downregulated after LR-MSC stimulated by TGF-β1 while LR-MSC could promote lung fibrosis by differentiating into myofibroblasts." (PMID 35508454, 2022).